ENSG00000252920
Synonyms: LOC124900435
Gene: Small nucleolar RNA gene on chromosome 1 (153,012,482 to 153,012,614, reverse strand). Ensembl gene ENSG00000252920.
Gene Ontology:
Biological process: RNA processing
Cellular component: nucleolus
Homologues: Orthologues: rat LOC120102627 (74% identical). Paralogues in human: SNORA31B (82% identical), SNORA31 (62% identical).